CD4 (CD4 molecule)
Diseases named in the same sentence as CD4 in open-access papers (continued):
Sharing a sentence is not in itself a finding about the gene and the disease.
tumor (continued). "Nevertheless, and despite high densities of T cells and TLS, only a small fraction of CD4+ and CD8+ T cells in the inflamed phenotype expressed the co-stimulatory receptors ICOS or 41BB, which co-ocurred with a significantly decreased MHC-II expression by tumor cells." (PMID 34580291, 2021). "In addition to CD4 T cells, therapeutic protein vaccine treatment highly enhanced CD8 T cell tumor infiltration and improved their TCR avidity and functionality—an effect further enhanced by combination with STINGa—while simultaneously increasing the expression of exhaustion markers PD-1 and Tim-3." (PMID 34276686, 2021). "RT increased OX40 expression on tumor infiltrating CD4+ non-regulatory T cells." (PMID 34868010, 2021). "Specifically, NK cells and especially CD4+ and CD8+ T cells from 77570 and 83942 overlapped, showing similar overall expression profiles and further suggesting their shared genetic alterations could shape similar tumor microenvironment." (PMID 33963182, 2021). "Suppression of TNBC lung metastasis by resveratrol may be through elevating local antitumor immunity, as revealed by an increase in the levels of type 1 cytokines, including IFN-γ and IL-2 in the lung and infiltration of CD4+ and CD8+ T cells to the lung of resveratrol-treated tumor bearing mice." (PMID 34948368, 2021). "However, the type of endogenous immune response to GBM and molecular mechanism that regulates tumor infiltrating CD4+ T-cell lineage in the TME is not known." (PMID 34012510, 2021). "The protein was found to have low regressions in the tumor and stromal compartments between blocks of YTMA454, a high correlation between its expression in the tumor versus stromal compartment, and modest correlations of expression with CD4 and CD8 in patients relative to other TIL and CAF markers." (PMID 34771664, 2021). "Given recent reports that the balance between effector and suppressor immune subsets may offer more useful prognostic information, we evaluated the correlation between ratios of CD8+/FOXP3+, CD3+/FOXP3+, CD4+/FOXP3+, and CD68+/CD163+ and survival in tumor samples at diagnosis and after NACT." (PMID 32852603, 2021). "Furthermore, we also observed an increase in CD4+ cells but a decrease in CD8+ T cells in lung and liver metastasis sites, indicating that DPP-4i may induce tumor-immunosuppressive microenvironment in metastatic sites." (PMID 34631556, 2021). "In addition, the percentage of CD4+ cells was higher (p = 0.02, fold change = 3.15) and percentage CD19+ cells was lower (p = 0.002, fold change = 0.45) in tumours treated with letrozole compared to vehicle-treated tumours." (PMID 34602068, 2021). "Meanwhile, tumor immune microenvironment analysis showed that Met@Man-MPs significantly increased the percentages of M1-like TAMs, CD8+ T cells, activated CD8+ T cells, and activated CD4+ T cells, while decreased the percentages of M2-like TAMs, MDSCs and Tregs." (PMID 33469052, 2021). "Our data shows that sensory overactivation induce an increase in the number of tumor-infiltrating anti-cancer lymphocytes (CD8 + T cells, CD4 + T cells, γδ T cells, and NK cells), while we did not detect changes in the number of tumor-infiltrating regulatory T cells." (PMID 34784974, 2021). "Moreover, in ICOS- or ICOS ligand (ICOSL)-deficient mice, the efficacy of anti–CTLA-4 therapy was significantly diminished, although the specific contribution of ICOS+CD4+ cells versus ICOS+CD8+ cells in tumor rejection was not addressed in this study." (PMID 33777008, 2021). "Our results showed significantly elevated B cells, CD4+ and CD8+ T cells, neutrophils, macrophages, and dendritic cells in the Glycolysis-H+M subgroup than in Glycolysis-L subgroup; this indicates that the immune patterns tend to be closely related to the glycolytic state of a tumor." (PMID 33686959, 2021).
tumor (continued). "Generally, the peritumor region and the whole tumor had higher CD4+ and CD8+ T cell percentage than the MPC region; on the other hand, compared with low MPC tumors, tumors with higher MPC tended to have more CD4+ and CD8+ T cell infiltration, especially at the peritumor regions." (PMID 34221970, 2021). "Previously, it was reported that differential activities of CD4 + T cells and CD8 + T cells may contribute to tumor immune escape, and that tumor-infiltrating dendritic cells (DCs) have a tumor-promoting activity through suppressing T-cell function, especially CD8 + T cells." (PMID 34066839, 2021). "However, our mouse model also allowed us to investigate TEG011_CD8α kinetics in the presence of tumor cells; and we observed sustained long-term TEG persistence mainly for γδTCR+CD4+CD8+ double-positive and a decline in γδTCR+CD8+ single-positive TEG011_CD8α cells." (PMID 34759930, 2021). "Actually, we did not know whether the detected CD4 + cells in the present study acted in favor of (TH1 subset) or against (TH2 subset) tumor growth." (PMID 34952631, 2021). "Furthermore, depletion of CD4+ and CD8+ cell populations in this treatment model prevented tumor regression, implying that both CTLs and CD4+ T helper cells play an indispensable role during pyroptosis-induced tumor clearance." (PMID 34429144, 2021). "However, the frequency of IL-21+CD4+ T cells was significantly increased in the tumor tissues compared with the paired adjacent non-tumor tissues (8.03 ± 4.37% vs. 2.4 ± 1.4%, respectively, P < 0.01)." (PMID 34026621, 2021). "Further analysis revealed that IL-4 released by CD4+ T cells was capable of polarizing macrophages into more M2-like state while suppressing the M1-like phenotype and promoting macrophage expression of EGF, which establishes the paracrine loop between tumor cells and macrophages." (PMID 33235291, 2021). "Furthermore, our data show striking inter patient variability in the epigenetic signature and key lineage specific CD4+ T cell transcription factor methylation status of tumor infiltrating CD4+ T-cell but not the CD4+ T cells from the blood." (PMID 34012510, 2021). "Yet, tumor cells may engage various escape mechanisms to acquire resistance to this response, which include induction of CD4+ T cell phenotype switching from proinflammatory anti-neoplastic TH1 cells into immunosuppressive and thus tumor growth-promoting Tregs." (PMID 35097027, 2021). "CD4+ helper T cells were thought to provide help for CD8+ T cells, but accumulated evidence supports the hypothesis that CD4+ T cells may play a central and indispensable role in anti-tumor immunity." (PMID 34885172, 2021). "Anti-CD4 antibodies have also shown benefit in non-hematologic malignancies via depletion of anti-inflammatory CD4 T cell subsets including Tregs, thereby allowing for enhanced proliferation of anti-tumor CD8 cytotoxic T cells." (PMID 34012443, 2021). "Also, it exhibits anti-tumor immune response by increasing T lymphocyte infiltration and decreasing PD-1 expression on CD8+ T lymphocytes and CD4+ and CD25+ regulatory T lymphocytes in caffein-treated groups in a carcinogen-induced local fibrosarcomas tumor model." (PMID 34975465, 2021). "However, CD39 expression by exhausted CD4 TILs could contribute to adenosine production in the context of the tumor microenvironment, where CD73 is expressed both by immune and tumor cells." (PMID 33332284, 2021). "Tumor CD4+ Th cells were lower (p<0.001) in old than young non-stressed mice." (PMID 34604038, 2021). "Notably, this therapeutic combination gave rise to a population of tumor-infiltrating CD4+ T cells with high expression of IFN-γ and TNF-α in response to re-stimulation with tumor antigens, suggesting that these cells were potent tumor antigen-specific Th1 cells." (PMID 33777008, 2021).
tumor (continued). "The protective role of the CD4+ T cells in our model could consist in their ability to induce an effective activation of CD8+ T cells and/or in their activity as direct effectors, since they were found infiltrating the tumor." (PMID 33717073, 2021). "However, CD8+ T cells infiltrated merely the margin of tumors in both IRE and control groups, which is because immune cells already inside the tumor are probably destroyed by IRE pulses, whereas, CD4+ T cells infiltrated both in the center and margin of the same tumor." (PMID 33882892, 2021). "This may be due to copious recognition of tumor antigen presented in the context to MHC class I (HY and OVA peptide specific mice) and subsequent TCR-mediated activation of CD8+ cells, while CD4+ T cells are TCR-activated only by antigen presenting cells that carry MHC class II molecules." (PMID 33669271, 2021). "The higher frequency of early stage exhausted CD8+ T cells (PD-1+ TIM3+) and later stage exhausted CD4+ T cells (PD-1+ LAG3+) in obese mice may offer an explanation for the faster tumour growth rate in the non-metastatic BC model." (PMID 34445503, 2021). "In addition, the analysis of the effect of viral etiology on tumor infiltrating lymphocytes by studying the expression of key markers of CD8+ T cells, CD4+ T cells, CD20+ cells, or CD68 macrophages again demonstrated the absence of correlation between viral pathology and biomarkers." (PMID 34503196, 2021). "Of note, naïve CD4+ T lymphocytes undergo polarization to Th subsets in response to a specific cytokine milieu, which in the TME is composed of a mixture of soluble factors belonging to pro- and anti-tumoral classes, with one class overcoming the other depending on tumor type and prognostic status." (PMID 34681881, 2021). "CD4+ T-cells in immunotype A may play an important role in recruiting and modulating cytotoxic T-cells in antitumor immunity and CD4+ T-cell activity contributes to the full function of CD8+ cytotoxic T-cells, which is effective for tumor control." (PMID 34708079, 2021). "CD8+ T cell depletion reversed the inhibition of tumor growth on day 10 but not on day 16 or at later time points in Fats−/− mice, suggesting that Fats−/− macrophages control tumor growth in a manner mainly dependent on CD4+ T cells." (PMID 34262035, 2021). "We further used the CIBERSORT algorithm to investigate the tumor-infiltrating immune cells, we found that the expression of KIFC1 was negatively correlated with the infiltration of naïve B cells, M2 macrophages, resting mast cells, resting natural killer (NK) cells, and resting memory CD4+ T cells." (PMID 35111813, 2021). "These outcomes mainly included the tumor response rate (e.g., objective response rate, disease control rate), quality of life (e.g., Karnofsky performance status), survival rate (e.g., 1-year, 2-years survival rate), immune function (e.g., CD3+, CD4+/CD8+ ratio), and tumor pain relief, among others." (PMID 35082677, 2021). "Tumor-infiltrating CD4+ or CD8+ T-cell frequency was not affected by AURKi treatment." (PMID 33123754, 2021). "To explore the potential translation of our preclinical findings to human cancers, we have also characterized peritoneal CD4+ and CD8+ T cells from 14 patients with peritoneal tumors undergoing surgical excision and examined these T cells for memory and functional phenotype and anti-tumor response." (PMID 33679747, 2021). "However, CXCR3 blockade significantly reduced CD8+ T cell infiltration, but not CD4+- or γδ T cell infiltration, into tumours." (PMID 33925140, 2021). "We performed a comprehensive analysis of tumor-infiltrating immune cells in a cohort of intrahepatic and extrahepatic BTC, including innate immunity members such as TLR7, TLR9, and adaptive immunity factors such as CD4 and CD8 as well as PD-1 and PD-L1 expression at protein level." (PMID 34573939, 2021).
tumor (continued). "For example, in the tumor microenvironment (TME), IFN-γ secreted by CD4+ and CD8+ T cells as an immune surveillance mechanism could upregulate PD-L1/PD-L2 in cancer cells, thereby contributing to tumor immune evasion via the IFN-γ-STAT1-PD-L1/L2 axis in melanoma." (PMID 34832863, 2021). "Similar to CD4+ T cells, activated naive CD8+ T cells can also proliferate and differentiate into various effector and memory cell types, including T effector cells, T memory stem cells, and T central memory cells, which are responsible for the elimination of tumor cells and viral infections cells." (PMID 34977871, 2021). "Interestingly, the NDV LX-mIL-7 vaccine displayed strong anti-tumor activity, with mIL-7 expression by the NDV LX strain inducing higher IFN-γ production, greater levels of tumor-infiltrating CD4+ and CD8+ T cells, and stronger cytotoxicity of tumor-specific CD8+ T cells than the NDV LX vaccine." (PMID 34956167, 2021). "Interestingly, in our study, PIKFYVE exhibited a negative correlation with CD8 T cells, activated memory CD4 T cells, follicular helper T cells, and regulatory T cells, all of which play important roles in monitoring tumor progression." (PMID 33968741, 2021). "In this study, 9 tumor-infiltrating immune cells were significantly correlated with the expression of CPNE8, among which B cells naive, mast cells resting, monocytes, T cells CD4 memory resting, and T cells regulatory (Tregs) were positively correlated with the expression of CPNE8." (PMID 34663825, 2021). "Taken together, these observations potentially point to an interplay between CD4 T cells (potentially regulatory T cells) and effector cells (i.e., CD8 T cells and NK cells) that emphasizes the importance of CD8 T cell activity as the main mediator of IL-12 anti-tumor activity." (PMID 34855754, 2021). "Moreover, Tumor Immune Estimation Resource (TIMER) results showed that the transcriptional levels of NEK2 were positively correlated with immune infiltration of B cells and CD4+ T Cell." (PMID 34834441, 2021). "It has not been addressed whether CD4+ T cells directly engage in tumor cell killing in the absence of Tregs, or whether they perhaps provide essential help for CD8+ T cell activation." (PMID 34632244, 2021). "The expression of T cell cytotoxicity (CD3G, CD3E, CD4, GZMA, PRF1 and TBX21), B cell MHC II and immune exhausted-related genes were abundant in metastatic sites; while MHC I inflammation related genes (HLA-B, HLA-C and IL-1A) were mostly higher in primary than recurrent tumor sites." (PMID 33476333, 2021). "Importantly, enhanced tumor recognition was restricted to CD4+ TEG011_CD8α cells and not CD4+ TEGLM1_CD8α mock cells, highlighting the specific role of CD8α as co-stimulation for the introduced FE11 γδTCR." (PMID 34759930, 2021). "Thus the tumor-specific antigen carried by Listeria can be presented through major histocompatibility complex (MHC) class I and MHC class II pathway to boost CD8+ T cell and CD4+ T cell immune responses." (PMID 34183739, 2021). "Analysis of bulk tumour mRNA displayed a strong correlation between ACTA2, a marker of MSCs, and matrix remodelling enzymes (MMP2), ECM proteins (VCAN, FN1, COL1A1), immunomodulatory molecules (Serpine1, CXCL12), innate immune cell markers (CD14, ITGAX) and adaptive immune cell markers (CD4)." (PMID 34885111, 2021). "In addition, the percentages of CD8 T cells, CD4 T cells and Tregs were all increased in the MC-38-irradiated and non-irradiated tumor-draining lymph nodes (TDLNs)." (PMID 34249740, 2021). "After challenging with Hepa129-mAFP-cells, tumor growth of HCC was very aggressive and showed increased recruitment of Treg, down-regulation of MHC-molecules, reduced amount of Th1 cytokines and poor infiltration with CD4+- and CD8+-T-cells or mature DC similar to human HCC." (PMID 34282787, 2021). "However, the precise molecular mechanisms by which IL-21-producing CD4+ T cells coordinate this anti-tumor effect are not well understood." (PMID 33809259, 2021).
tumor (continued). "Nevertheless, the loss of KDM6B resulted in TH2 and TH17 differentiation, indicating that the targeting of KDM6B might not improve anti-tumor CD4+ T cell responses." (PMID 33859645, 2021). "Interestingly, YAP1 KO CD4 and CD8+ T cells demonstrated superior tumor infiltration compared to wild-type counterparts, and tumor growth was either greatly delayed or nearly absent in tumor-bearing CD4–Cre or Foxp3–Cre mice." (PMID 34685695, 2021). "Similarly, in the CT2A tumor model, ZIKV treatment elicited an increase in numbers of CD45+ leukocytes (~4-fold), including CD4+ T cells (~7.5-fold), CD8+ T cells (~8.9-fold), NK cells (~2-fold), NKT cells (~2-fold), and Trm cells (~8-fold), compared with control-treated mice." (PMID 33232299, 2021). "This key CD4+ T cell help occurs through the licensing of dendritic cells (cDC1) through their interaction with MHC II and CD40/CD40L on CD4+ T cells, which was recently demonstrated in vivo in tumors, and resulted in successful cross presentation of tumor antigens to CD8+ T cells." (PMID 33708224, 2021). "This tumor growth delay was underpinned by elevated serum interleukin-6 (IL-6) levels, a lower percentage of central memory CD4+ T cells in the spleen, and a larger percentage of CD4+ T cells and effector memory CD8+ T cells in nonirradiated tumors." (PMID 36405502, 2021). "This 45-nucleotide long aptamer could recognize both murine and human PDL1 and modulate the tumor microenvironment by elevated CD4+ and CD8+ T cell infiltration and IL2, IFNγ, TNFα and other chemokine expression at the tumor site, which might form a loop against tumor proliferation." (PMID 34575825, 2021). "From an immunological perspective, IDH1(R132H) represents a potential immunotherapy target because it is a tumor-specific potential neoantigen that is indeed presented in major histocompatibility complex class II (MHCII) and can, thus, evoke a robust immune response in CD4+ T cells." (PMID 34203535, 2021). "Additionally, neither the percentage of CD3+CD4+ nor the percentage of CD3+CD8+ cells was correlated with tumor size (r = −0.163, p = 0.612 and r = 0.253, p = 0.428, respectively)." (PMID 34257554, 2021). "In addition, increased populations of both CD4+ and CD8+ T cells within GBM tumours were observed." (PMID 33964937, 2021). "Furthermore, the mechanistic studies suggested that the MOA of the antitumor synergy involves improved tumor vasculature normalization and enhanced T-cell mediated immunity, including increased tumor infiltration of CD8+ and CD4+ T cells and reduced double-positive CD8+PD-1+ T cells." (PMID 34686154, 2021). "Interestingly, depletion of CD8 cells alone, or depletion of both CD8 and CD4 cells, but not depletion of CD4 cells alone, significantly abrogated tumor growth inhibition by RGS treatment." (PMID 34092233, 2021). "In order to determine whether FGFR4 effectively reflected the status of the tumor immune microenvironment (TIME), the relationships between the FGFR4 and six TIICs (B cells, CD4 T cells, CD8 T cells, neutrophils, macrophages, and dendritic cells) were analyzed by TIMER online tool." (PMID 33407583, 2021). "Tumor-cell-extrinsic mechanisms of immunotherapy resistance involve components other than tumor cells within the tumor microenvironment, including increased distribution of Th2 cells, M2 macrophages, and decreased tumor-infiltrating CD8+ T cells, DCs, Th1 cells, CD4+ T cells, and M1 macrophages." (PMID 34622157, 2021). "CD4+Foxp3+CD25+ Tregs are exclusively enriched in the TME through their recruitment by cytokines/chemokines and certain growth factors, namely vascular endothelial growth factor and transforming growth factor-β, exerting an anti-tumour immune response and tumour evasion." (PMID 34062862, 2021).